BARD1 (BRCA1 associated RING domain 1)
Diseases named in the same sentence as BARD1 in open-access papers (continued):
Sharing a sentence is not in itself a finding about the gene and the disease.
Hereditary breast cancer (6 papers, 2019 to 2021). Breast carcinoma that has developed in relatives of patients with history of breast carcinoma. "The percentage of deleterious BARD1 variants in the subset of patients with hereditary breast cancer (HBC) was 0.50%, 0.42% in hereditary ovarian cancer (HOC) cases and 0.33% in patients with HBOC." (PMID 33498765, 2021).
Lynch syndrome (6 papers, 2012 to 2024). An autosomal dominant hereditary neoplastic syndrome characterized by the development of colorectal carcinoma and a high risk of developing endometrial carcinoma, gastric carcinoma, ovarian carcinoma, renal pelvis carcinoma, and small intestinal carcinoma.
acute myeloid leukemia (5 papers, 2013 to 2025). Acute myeloid leukemia (AML) is a group of neoplasms arising from precursor cells committed to the myeloid cell-line differentiation. "The detection and characterization of oncogenic isoforms in BARD1 were recently reported in acute myeloid leukemia (AML), a cancer affecting the precursors of erythrocytes, granulocytes, monocytes, and platelets in adults." (PMID 32708251, 2020). "Here, we investigate BARD1 expression and function in human acute myeloid leukemias and its modulation by epigenetic mechanism(s) and microRNAs." (PMID 24349422, 2013). "BARD1 expression has been found to be down-regulated in samples from myelodysplastic syndrome patients (MDS) with progression to acute myeloid leukemia (AML)." (PMID 24349422, 2013). "Interestingly, miR-19a-3p has been already described as regulator of BARD1 expression in acute myeloid leukemia cells." (PMID 29217833, 2017). "BARD1 isoforms, including exon 6 to exon 11 (truncated isoforms), were highly expressed in acute myeloid leukemia (AML) ex vivo blasts compared to FL- BARD1 expression level." (PMID 35650591, 2022).
non-small cell lung carcinoma (5 papers, 2013 to 2025). A group of at least three distinct histological types of lung cancer, including non-small cell squamous cell carcinoma, adenocarcinoma, and large cell carcinoma. "BARD1 isoforms have also been detected in NSCLC (Non-Small Cell Lung Cancer) samples and their expression correlated with decreased survival." (PMID 24349422, 2013). "Another gene BARD1, whose isoforms may be related to tumor initiation and invasive progression, was a more suitable neoteric prognostic marker for non-small-cell lung cancer." (PMID 24643254, 2014).
leukemia (4 papers, 2013 to 2021). A malignant (clonal) hematologic disorder, involving hematopoietic stem cells and characterized by the presence of primitive or atypical myeloid or lymphoid cells in the bone marrow and the blood. "Our experimental results show that after treatment with Stattic, the level of ATM mRNA in leukemia cells is lower, and after Stattic and VP-16 treatment of cells, the expression of BRCA1, BARD1, RAD51, and polδ in the HR pathway are all downregulated." (PMID 33796529, 2021).
lung adenocarcinoma (4 papers, 2018 to 2024). A carcinoma that arises from the lung and is characterized by the presence of malignant glandular epithelial cells. "BAP1 is a tumor suppressor gene that contains binding domain for BRCA1 and BARD1; germline mutations predispose patients to a variety of cancers including uveal and cutaneous melanoma, mesothelioma, lung adenocarcinoma, meningioma, and renal cell carcinoma." (PMID 38700789, 2024). "A patient with lung adenocarcinoma and with a homozygous stop-gain mutation in BARD1 (G320*) and a duplication event in RBBP8 (e3–4 duplication) was also classified as HRD by HRDetect but not by CHORD." (PMID 36964191, 2023). "Additionally, the lncRNA BARD1 9′L, which stimulates the expression of BARD1-FL and isoforms β, δ, and γ through interaction with the 3′ UTR of BARD1, was significantly upregulated in lung tumors compared to paired cancer-free lung tissue as well as in the human lung adenocarcinoma cell line, A549." (PMID 32708251, 2020).
bladder cancer (3 papers, 2023 to 2024). "Our observations suggest the potential value of the expression pattern of BARD1 at specific subtypes of bladder cancer." (PMID 37474724, 2023). "The expression of ERBB2, RAD21, RAD50 and BARD1 mRNA levels was assessed in The Cancer Genome Atlas (TCGA) bladder cancer dataset along with four validation cohorts." (PMID 37474724, 2023). "Importantly, here we showed that high RAD21, RAD50 or BARD1 mRNA expression in bladder cancer patients with low-ERBB2 exhibit poor survival." (PMID 37474724, 2023). "In this current investigation we examined RAD21, RAD50 or/and BARD1 co-expression with different status of ERBB2 expression and assessed their prognostic and clinical significance in bladder cancer." (PMID 37474724, 2023). "This study evaluates the biological and prognostic significance of RAD21, RAD50 and BARD1 (homologous recombination biomarkers) mRNA levels with ERBB2 low and high expression to explore their impact on bladder cancer patient survival and cancer aggressiveness." (PMID 37474724, 2023). "Moreover, in 413 bladder cancer samples (data derived from TCGA), a significantly higher expression level of four genes, RAD21, RAD51, BARD1, and ERBB2, was observed in ERBB-low as compared to ERBB-high tumours." (PMID 39080120, 2024). "This implies that BARD1 mRNA may be a promising prognostic marker for bladder cancer patients, irrespective of the tumor grade or stage." (PMID 37474724, 2023).
clear cell carcinoma (3 papers, 2005 to 2022). "In addition, a germ line missense mutation in the BRCA1 associated protein BARD1 can give rise to independent tumors in the breast, ovary (clear cell carcinoma) and endometrium (also a clear cell carcinoma)." (PMID 15918899, 2005). "Only one clear cell carcinoma underwent extended sequencing, and this case showed both PTEN and BARD1 mutations." (PMID 34680387, 2021).
endometrial cancer (3 papers, 2016 to 2025). Primary or metastatic malignant neoplasm involving the endometrium (mucous membrane that lines the endometrial cavity).
endometriosis (3 papers, 2019 to 2023). The growth of functional endometrial tissue in anatomic sites outside the uterine body. "As our results showed that BARD1 was associated with hypoxia and ROS in endometriosis, we examined the regulatory role of miR-210-3p in targeting BARD1 in the cell cycle and cell proliferation by co-infection with LV-In-210 and LV-In-BARD1." (PMID 30760709, 2019). "As a novel target of endometriosis, BARD1 requires more attention to clarify its role in endometriosis progression, prediction and therapy." (PMID 30760709, 2019). "Here we find that the DNA damage response protein BARD1 is a target of miR-210-3p, and the BRCA1 complex is implicated in cell cycle regulation response to DNA damage under hypoxia in endometriosis." (PMID 30760709, 2019). "On multivariate analysis, BARD1 expression still significantly negatively correlated with endometriosis severity (P = 0.047), while endometriosis stage showed a positive correlation." (PMID 30760709, 2019). "By chi square tests, we found that the lesion size, chronic pelvic pain score, endometriosis stage and rAFS score were significantly lower in BARD1-positive patients than in BARD1-negative patients (P < 0.05)." (PMID 30760709, 2019). "Studying the correlation between BARD1 and endometriosis severity may help elucidate the function of miR-210-3p in endometriosis." (PMID 30760709, 2019). "Univariate linear regression analyses revealed that lesion size, chronic pelvic pain score, dysmenorrhoea pain score and endometriosis stage were positively correlated with endometriosis severity, which was based on rAFS score, while BARD1 H-score showed a negative correlation (P < 0.01)." (PMID 30760709, 2019). "Moreover, no studies have demonstrated roles for BARD1 and BRCA in endometriosis." (PMID 30760709, 2019).
gynecological cancers (3 papers, 2020 to 2023). "In a mutational study that included different types of gynecological cancers, ovarian, breast, and uterine tumors, seven polymorphisms were identified within the coding sequence of BARD1, including somatic missense mutations and germline alterations." (PMID 35650591, 2022). "Interestingly, few of the genetic mutations discussed here are present in and influence the risk of developing breast and gynecological cancers, suggesting that some of these BARD1 SNPs may be cancer-specific." (PMID 32708251, 2020). "We will then describe different variations of BARD1 present in non-breast and non-gynecological cancers, which are not driven by mutations in either BRCA1 or BRCA2 genes." (PMID 32708251, 2020). "Intriguingly, recent genome-wide studies have identified various single nucleotide polymorphisms (SNPs), genetic alterations, and epigenetic modifications in or near the BARD1 gene that manifested profound effects on tumorigenesis in a variety of non-breast and non-gynecological cancers." (PMID 32708251, 2020).
Li-Fraumeni syndrome (3 papers, 2017 to 2021).
melanoma (3 papers, 2021 to 2022). A malignant, usually aggressive tumor composed of atypical, neoplastic melanocytes. "Nanopore and Sanger sequencing has identified two other BARD1 splice variants of interest in melanoma: BARD1 Δ(E3_E9) and IVS10+131▼46." (PMID 33672422, 2021). "The results show that previously identified BARD1 mRNAs encoding isoforms, as well as novel splice isoforms, can be detected using both long-range nanopore sequencing, in addition to short-read and targeted approaches, including RNA-Seq and RT-qPCR in both melanoma cell lines and tissue samples." (PMID 33672422, 2021). "Herein, we present the first study assessing the expression of BARD1 mRNA splice isoforms in melanoma cell lines and archival formalin-fixed paraffin-embedded (FFPE) tissue samples." (PMID 33672422, 2021). "In melanoma cell lines, however, nanopore sequencing identified the expression level of BARD1-β comprised <1% of total BARD1 transcripts." (PMID 33672422, 2021). "In conclusion, we identified multiple alternative transcripts corresponding to known BARD1 isoforms, expressed at much higher levels than BARD1-FL in both melanoma and melanocytes." (PMID 33672422, 2021). "We additionally sequenced four novel BARD1 splicing events in the melanoma cell lines, several of which we are reporting for the first time." (PMID 33672422, 2021). "Herein, we present, for the first time, the expression of alternative BARD1 splice isoforms in various melanoma samples." (PMID 33672422, 2021). "Taken together, the relatively high expression of BARD1-δ, BARD1-ε, and BARD1-η, compared to BARD1-FL in melanoma cells, suggests a role for these transcripts in uncontrolled melanoma cell proliferation and mitochondrial regulation in response to stress." (PMID 33672422, 2021). "Using long-range nanopore sequencing, RT-qPCR, and RNA sequencing analyses, we examined the transcription of BARD1 splice isoforms in melanoma cell lines and patient tissue samples." (PMID 33672422, 2021). "Nevertheless, using nanopore sequencing technology, we unexpectedly found that what are usually rare and potentially antagonistic isoforms of BARD1 transcription are in fact expressed at relatively high levels in melanoma and melanocytes." (PMID 33672422, 2021). "However, the expression levels of the BARD1-FL transcripts were very low in all NZM melanoma cell lines, as measured by nanopore sequencing." (PMID 33672422, 2021). "As such, increased levels of BARD1-δ expression relative to BARD1-FL may regulate or inhibit tumour suppressor functions in melanoma cell lines." (PMID 33672422, 2021). "We carried out the first detailed analysis of alternative BARD1 transcription in melanoma." (PMID 33672422, 2021). "Moreover, using the nanopore sequencing of BARD1 mRNA transcripts in melanoma, we identified the full-length BARD1 isoform, along with five other major alternatively spliced transcripts." (PMID 33672422, 2021). "However, due to the recognition of BARD1’s pleiotropic roles in DNA repair processes, in addition to the high mutation burden commonly observed in melanoma, we hypothesised a pro-tumorigenic role for alternate BARD1 isoforms in melanoma." (PMID 33672422, 2021). "Currently, investigations into BARD1 splice isoforms in melanoma are not present in the literature." (PMID 33672422, 2021).
uterine cancer (3 papers, 2012 to 2025). Primary or metastatic malignant neoplasm involving the uterine corpus and/or the cervix. "BRCA1-associated RING domain 1 (BARD1) gene has also been identified as an important tumor suppressor gene in breast, ovarian, and uterine cancers." (PMID 32708251, 2020). "In contrast, both germline and somatic BARD1 mutations are found in sporadic breast, ovarian and uterine cancers." (PMID 23056176, 2012). "Germ line and somatic mutations in BARD1 are found in sporadic breast, ovarian and uterine cancers." (PMID 23056176, 2012).
Cachexia (2 papers, 2020 to 2024). Severe weight loss, wasting of muscle, loss of appetite, and general debility related to a chronic disease. "In this study we show that systemic upregulation of Zip14 in muscle is associated with severe cachexia in the Bard1‐deficient, orthotopic model." (PMID 32730698, 2020). "We show that upon orthotopic injection into the mammary fat pad of mice, Bard1‐deficient cells spontaneously metastasize to the lung and induce cachexia in multiple muscles." (PMID 32730698, 2020). "We therefore investigated whether cachexia development in the Bard1‐deficient, orthotopic metastasis model is associated with the upregulation of Zip14 in muscle." (PMID 32730698, 2020). "While tumor growth in Brca1-def models was monitored for 13 weeks post tumor-cell injection, Bard1-def models could only be monitored for 5 weeks due to the onset of cachexia, as described in our previous studies." (PMID 38956205, 2024). "Knowledge of the specific factors that regulate Zip14 induction in muscle cells in the Bard1‐deficient, orthotopic model could therefore inform new therapeutic opportunities to prevent or reverse cachexia in triple‐negative breast cancer models with disrupted Brca1/Bard1 function." (PMID 32730698, 2020).
developmental delay (2 papers, 2019 to 2023). "Copy number alterations in the BARD1 locus have been associated with developmental delays, including coarctation of the aorta during early organogenesis and heart development." (PMID 37926287, 2023).
esophageal cancer (2 papers, 2023 to 2024). A primary or metastatic malignant neoplasm involving the esophagus. "Additionally, GSEA enrichments revealed the suppression of cell cycle and mitotic checkpoint regulatory (AURKB, PLK1, and E2F) and the DDR and DNA-repair (ATR, BARD1, and FANCONI) pathways by STL001 in esophageal cancer." (PMID 38697979, 2024).
germ cell tumor (2 papers, 2021 to 2023). A benign or malignant, gonadal or extragonadal neoplasm that originates from germ cells. "Germline truncating mutations of PALB2 (c.3350+5G>A, splice region) and BARD1 (p.Q206fs) were detected in immature teratomas (classified as germ cell tumors), which showed particularly high HRD scores." (PMID 35676859, 2023). "This study determines the expression level of BARD1 and its isoform beta (β) in three different histogenetic groups of pediatric cancer—neuroblastic tumours, and for the first time in chosen germ cell tumours (GCT), and rhabdomyosarcoma (RMS), using the qPCR method." (PMID 33530592, 2021). "Importantly, here we report for the first time the expression of BARD1 in other childhood cancers, including germ cell tumours (GCTs) and rhabdomyosarcoma (RMS)." (PMID 33530592, 2021).
hereditary cancer syndrome (2 papers, 2020 to 2023). "The PALB2-associated hereditary cancer syndrome is also associated with pancreatic cancer, while the BARD1-associated hereditary cancer syndrome is associated with colon cancer." (PMID 37239385, 2023). "There have been a number of reports of BARD1 variants in the context of hereditary cancer syndromes: 160 pathogenic, 19 pathogenic or likely pathogenic, 56 likely pathogenic, and 1131 variants of uncertain significance." (PMID 32726901, 2020). "This led to the hypothesis that variants in BARD1 could encode an aberrant protein affecting the interaction with BRCA1 and predispose to BC and/or OC, especially in hereditary cancer syndrome families not accounted for by BRCA1 or BRCA2." (PMID 32726901, 2020).
liver cancer (2 papers, 2017 to 2025). An epithelial or non-epithelial malignant neoplasm that arises from the liver. "BARD1 has also be found as prognosis-related genes of liver cancer and used for predicting the survival of liver cancer patients." (PMID 40805222, 2025). "Elevated BARD1 expression was positively correlated with tumor-node-metastasis stage, Barcelona-Clinic Liver Cancer stage, hepatitis B surface antigen, large tumor size, serum alpha-fetoprotein levels, and serum aspartate aminotransferase levels." (PMID 28794477, 2017).
metastatic prostate carcinoma (2 papers, 2021 to 2022). A carcinoma that arises from the prostate gland and has spread to other anatomic sites. "In another study of 704 men with metastatic prostate cancer, only one BARD1 mutation was detected (0.14%) compared to 0.09% in 54,802 reference controls from Genome Aggregation database (p = 0.46)." (PMID 34771627, 2021). "No BARD1 mutations were detected in 692 men with metastatic prostate cancer unselected for age and family history of cancer." (PMID 34771627, 2021).
Nephroblastoma (2 papers, 2018 to 2020). An embryonal neoplasm characterized by the presence of epithelial, mesenchymal, and blastema components. "This single study highlights the need for identification of functions of aberrant BARD1 in nephroblastoma initiation and progression, particularly by expanding patient samples to include other ethnic groups and analyzing the frequency of more SNPs in the BARD1 gene." (PMID 32708251, 2020).